TERT (telomerase reverse transcriptase)
Diseases named in the same sentence as TERT in open-access papers (continued):
Sharing a sentence is not in itself a finding about the gene and the disease.
cancer (continued). "TERT has long been suggested as an attractive target for cancer therapy, and it will be interesting to test if it will be possible to simultaneously inhibit all these three signaling cascades by targeting TERT, thus killing many birds with one stone." (PMID 31284662, 2019). "Examining the TERT-associated mutation/SCNA list, we found 8 drug targets with mutations/SCNAs across cancer types." (PMID 31179925, 2019). "TERT mRNA levels were drastically reduced in cancer cells which transiently overexpressed PBX4 or MEIS3 combinatorially with HOXC5 to transcriptionally repress TERT." (PMID 29614790, 2018). "Recently, this synergistic effect of BRAF and TERT promoter has been demonstrated as BrafV600E → MAPK pathway → FOS → GABP → TERT signaling/transcription axis in human cancers." (PMID 30619082, 2018). "Undoubtedly, understanding how the dormant TERT promoter is reactivated during carcinogenesis is central to understanding the mechanisms of cancer progression." (PMID 30093619, 2018). "As incessant synthesis of telomeric DNA is necessary for unlimited cancer cell proliferation, 85–90% of human tumors reactivate TERT expression." (PMID 30093619, 2018). "To further confirm the specificity of the RNAscope assay, we analyzed TERT expression in two cancer cell lines known to express telomerase (LOX and HCT116) and two fibroblast cell lines known to be telomerase negative (WI38 and MRC5)." (PMID 30517099, 2018). "Certain hints have emerged which highlighted that miRNA effectively inhibited positive regulators of TERT in different cancers." (PMID 29614790, 2018). "Transcription of the TERT gene is probably the key determinant in regulating telomerase activity, since TERT transcription is specifically up-regulated in cancer cells but silent in most normal ones." (PMID 29643934, 2018). "ITGB1 was quantitatively controlled by miR-29a in cancer cells and astonishingly, TERT negatively regulated miR-29a expression." (PMID 29614790, 2018). "These clues are opening new horizons for investigation of extra-telomeric roles of TERT in different cancers." (PMID 29614790, 2018). "TERT can also alleviate levels of cellular reactive oxygen species (ROS) by enhancing cellular antioxidant defense systems, thus allowing cancer cells to evade death stimuli and can stimulate the epithelial-mesenchymal transition and induce stemness." (PMID 29643934, 2018). "Among them, few are used, as telomerase inhibitor by targeting of telomerase RNA (TR) or telomerase reverse transcriptase (TERT), in combination with irradiation to enhance cancer cells response to irradiation via telomere shortening (Telomere dysfunction)." (PMID 30405890, 2018). "The telomerase catalytic component telomerase reverse transcriptase (TERT) is expressed in over 80% of human cancers and is thought to be rate limiting for telomerase activity." (PMID 29616301, 2018). "The limiting determinant of telomerase activity is the catalytic component TERT, and TERT expression is closely correlated with telomerase activity and cancer initiation and disease progression." (PMID 29568354, 2018). "The classical function of TERT is to add telomeres at the end of chromosomes, preventing critical telomere shortening, thus enabling cancer cells acquire replicative immortality." (PMID 29422527, 2018). "TERT is the gene showing the second most significant signal of negative selection (Q < 0.001) and it has been described as an oncogene in cancer progression." (PMID 29855388, 2018). "It has been persuasively documented that TERT over-expression played central role in cancer development and progression." (PMID 29614790, 2018). "TERT activation in different cancers has fuelled extensive research, producing sufficient knowledge about structure and functions of telomerase-associated machinery." (PMID 29614790, 2018).
cancer (continued). "Elevated TERT expression contributes to telomerase-dependent maintenance of telomeres that is often required for long-term proliferation and survival of cancer cells." (PMID 29439385, 2018). "Use of antisense oligonucleotides against miR-21 markedly reduced STAT3 and TERT in treated cancer cells." (PMID 29614790, 2018). "In multiple studies, normal human somatic cells that do not express TERT are associated with unmethylated or hypomethylated promoters, while some cancer lines with completely hypermethylated TERT promoter regions express TERT." (PMID 29439385, 2018). "Given the wealth of knowledge unfolding extra-telomeric roles of TERT in different cancers, this review confines itself to the theme elucidating miRNA regulation of TERT in various cancers." (PMID 29614790, 2018). "Robust RNAscope TERT signal was observed in the cancer cell lines, while only extremely rare RNAscope TERT spots were seen in the fibroblast cell lines." (PMID 30517099, 2018). "TERT and CLTPM1L are the two promising candidate genes associated with cancer susceptibility in Chr5p15.33." (PMID 29695979, 2018). "Here, the authors elucidate the structural basis for p52/ETS1 binding to mutant TERT, suggesting a general mechanism for TERT reactivation in cancer." (PMID 30093619, 2018). "Future studies into the impact of human integrating viruses on DNA methylation and TERT expression in human cancers offers an exciting direction to test our observations observed in chicken tumors." (PMID 29439385, 2018). "On the one hand, increased TERT expression correlates with the hypermethylation of the TERT promoter region in many human cancers." (PMID 29439385, 2018). "This study is the first to identify that miR-128 targets TERT mRNA and reduces TERT mRNA and protein levels resulting in a decrease in telomerase activity in cancer cells." (PMID 29568354, 2018). "Use of miRNA-based therapeutics against TERT in different cancers needs detailed research in preclinical models for effective translation of laboratory findings to clinically effective therapeutics." (PMID 29614790, 2018). "Future studies must converge on unraveling the effects of changes in 3′UTR of TERT and how it influenced miRNA mediated targeting of TERT in different cancers." (PMID 29614790, 2018). "In this review, we have comprehensively discussed how different miRNAs regulate TERT in different cancers." (PMID 29614790, 2018). "Maintenance of telomeres is required for the indefinite proliferative potential of cancer cells and TERT activity can be measured in 80–90% of cancers." (PMID 29874793, 2018). "TERT, a catalytic subunit of the enzyme telomerase, is critical for telomerase activity and has great importance in cancer progression." (PMID 29534075, 2018). "miRNA regulation of TERT has added new layers of information to an already complex role of TERT in different cancers." (PMID 29614790, 2018). "This table summarizes correlation analyses between: (a) Myc and TERT expression, (b) Myc expression and telomerase activity in various types of cancers." (PMID 28184371, 2017). "A number of studies have reported that single nucleotide polymorphisms (SNPs) of TERT and TERC gene are associated with a significantly higher susceptibility to multiple types of cancers." (PMID 29299136, 2017). "While some of these transcription factors can regulate TERT expression in cancers, there is a distinct subset of cancers that display recurrent mutations in the TERT promoter, resulting in the binding of new transcription regulators." (PMID 28264499, 2017). "Although decreased binding of transcription factor ETS2 can modify the expression of the gene, opinions differ on its effect on the level of TERT expression in cancer cells." (PMID 29100407, 2017). "The correlation between Myc and TERT mRNA expression has been extensively investigated in cancers for two reasons." (PMID 28184371, 2017).
cancer (continued). "As an alternative to upregulation of TERT expression, cancers can also use the ALT pathway for telomere maintenance, associated with inactivating mutations in either the ATRX or DAXX genes." (PMID 29312603, 2017). "Based on these known facts, considerable new strategies including RNAi have been explored to target the TERT gene for cancer gene therapy." (PMID 28420995, 2017). "Disrupting the transcriptional activation of TERT at mutant TERT promoters represents a promising therapeutic strategy for the treatment of a subset of cancers with mutant TERT promoters." (PMID 28264499, 2017). "Although mechanisms of post-translational and post-transcriptional control of TERT have been elucidated, the predominant form of regulation across many cancer types is the transcriptional control." (PMID 29045464, 2017). "TERT, the ‘Cancer census gene’ exhibiting the most frequent copy number gain in the TCGA-set, encodes the catalytic component of the telomerase enzyme." (PMID 29371938, 2017). "Regulation of telomerase activation in cancer is complex and multifactorial and involves transcriptional activation of the TERT gene." (PMID 29100407, 2017). "It is worth mentioning that TERT is the catalytic protein subunit of telomerase, and it is important for maintaining the activity of telomerase in cancer cells." (PMID 28420995, 2017). "TERT upregulation is observed in certain murine cancers such as breast, skin while the ectopic expression of TERT has been found to stimulate cell proliferation." (PMID 28264499, 2017). "The cancer risk genotypes rs2736098_TT and rs2736100_CC are intimately associated with HCC tumors bearing a wt TERT promoter." (PMID 28416747, 2017). "We utilized a custom-designed panel that covered up to 381 cancer-related genes curated from the literature, as well as the TERT promoter and introns that contain frequent breakpoints for selected fusion candidates." (PMID 29123093, 2017). "In summary, we discuss the way forward to better understand the interplay between Myc and TERT in normal physiology and cancer." (PMID 28184371, 2017). "This TERT overexpression is detected in up to 90% of cancer cells, compared to in <20% of normal cells." (PMID 28947783, 2017). "TERT is expressed in cancer cells to achieve limitless replicative potential, and increased TERT expression is observed in 90% of human HCC." (PMID 28969016, 2017). "Recently, studies indicated hypermethylation of the TERT promoter ubiquitously exists in highly proliferative cancer cells and correlates with increased Telomerase activity." (PMID 28002788, 2017). "Estrogen has been shown to increase Myc expression and thus indirectly induce TERT transcription, although direct binding of the estrogen receptor (ER) to the TERT promoter has also been demonstrated in ER-positive cancers." (PMID 28184371, 2017). "The first being that simultaneous deregulation of Myc and TERT is a frequent genetic event occurring in several cancers." (PMID 28184371, 2017). "Telomerase reconstitution by reactivating TERT expression is known to occur in cancers by various mechanisms that involve oncogenic transcription factors, gene amplification, promoter mutations, crosstalk with oncogenic pathways or epigenetic regulation." (PMID 28184371, 2017). "Although these findings suggest that telomerase activation plays a role in cell immortalization in both entities, TERT is commonly altered in a variety of cancers." (PMID 28267263, 2017). "TERT, the catalytic subunit of telomerase, plays a critical role in maintaining telomere length and has been shown to support cancer progression through both telomere-dependent and telomere-independent mechanisms." (PMID 28212542, 2017). "In a more recent study, the interaction of TERT and p65 was found to be crucial for regulating the expression of NF-κB target genes which are essential for inflammation and cancer development." (PMID 28264499, 2017).
cancer (continued). "We also discuss future perspectives in investigating the regulation of Myc at TERT promoter during cancer development." (PMID 28184371, 2017). "Disruption of promoter methylation, chromatin modifications and structural changes mediated by CTCF can lead to the dysregulation of cancer-associated genes, including RARRES1, HOXA10, TERT and PTGS2." (PMID 28977939, 2017). "In previous studies, several genes involved in the glycolytic pathway were shown to be downregulated following TERT knockdown, suggesting that TERT directly regulates cancer cell metabolism, especially glycolysis." (PMID 28790533, 2017). "In most cancers, high expression of Myc and TERT (measured as mRNA expression or telomerase activity) occur together, suggesting positive correlation." (PMID 28184371, 2017). "High resolution HLA typing revealed homozygous HLA-A*0201 allele, which is the globally prevalent HLA class I allele that has been used to study cancer vaccines for years and recently to develop universal cancer vaccine targeting TERT-derived peptides." (PMID 28245875, 2017). "Human telomerase reverse transcriptase (TERT), a catalytic subunit of telomerase, plays a critical role in the pathology of aging and cancer by maintaining genome integrity and controlling cell proliferation." (PMID 28460432, 2017). "TERT shows little expression in normal somatic cells but is commonly re-expressed in cancers, facilitating immortalization." (PMID 29262649, 2017). "GABP (GA-binding protein) selectively activates the mutant TERT promoter in cancer which in turn enables cells to escape apoptosis, fundamental steps in the initiation of human cancer." (PMID 28592245, 2017). "In particular, the SNP rs2853669 (T > C), located at -245 bp from the TERT ATG site, is associated with the risk of various cancers such as breast cancer, lung cancer, and hepatocellular carcinoma; however, these results remain inconclusive." (PMID 28881610, 2017). "Recently, a number of investigations have been conducted to study the potential influence of Telomerase reverse transcriptase (TERT) and cleft lip and palate transmembrane 1-like (CLPTM1L) gene variation on cancer susceptibility." (PMID 29254260, 2017). "By contrast, in the MED12-wild type pathway, borderline and malignant PTs are more likely to develop de novo, and driven by early genetic alterations in TERT and/or other cancer genes." (PMID 29043292, 2017). "In the late tumorigenesis events, cancer cells develop mobilization and extravasation skills that promote the metastatic dissemination via TERT overexpression." (PMID 29152058, 2017). "The TERT promoter region that we chose for the present study was based on the result obtained from cancer cell lines." (PMID 26870890, 2016). "Together, recent findings firmly established that the genetic alterations at the TERT promoter play a central role for the cancer-specific telomerase activation." (PMID 27403431, 2016). "Parallel in vitro studies have provided preliminary evidence supporting a direct role for telomerase in drug resistance: Ectopic overexpression of TERT in cancer cell lines rendered them less sensitive to radiation and imatinib." (PMID 27240403, 2016). "Telomerase reverse transcriptase (TERT) is a gene within the cancer susceptibility region located at Chr5p15.33, which is associated with multiple cancer types." (PMID 27825130, 2016). "SRSF11, a multifunctional nuclear protein also regulated by miR‐10b, among its other activities triggers alternative splicing of TERT, telomerase reverse transcriptase, gene critical for cancer stem cells self‐renewal." (PMID 26881967, 2016). "This study, together with recent studies in other cancers, unequivocally establishes an essential role of TERT in cancers." (PMID 27185198, 2016).
cancer (continued). "What is the relationship between the mutant promoter and many other TERT signaling cascades and regulators, and is targeting the mutant promoter feasible and sufficient for telomerase inhibition in cancer cells?" (PMID 27438857, 2016). "After the discovery of the enzyme in humans, TERT had initially only been attributed to germ line cells, stem cells and cancer cells." (PMID 27322328, 2016). "Although TERT is dowregulated in most non-dividing mammalian tissues, it was shown that overexpression of TERT in epithelial tissue in cancer resistant mice leads to increased median lifespan." (PMID 27695477, 2016). "Chromosome 5p15.33, which contains at least two plausible candidate genes, TERT and CLTPM1L, is a unique cancer susceptibility locus associated with about 10 distinct cancers." (PMID 27825130, 2016). "Other therapeutic strategies have sought to exploit the active promoter-driven expression of TERT or TERC in cancer to express cytotoxic agents in target cells." (PMID 27240403, 2016). "In cancer cells, TERT expression is induced by several cellular transcription factors including NF-kB, β-catenin, and c-Myc." (PMID 27501725, 2016). "CLPTM1L is frequently upregulated in cancer cells and shows preserved colocalization with the TERT locus for a shared synteny in many species." (PMID 27977688, 2016). "GV1001 is a telomerase-based cancer vaccine made of a 16-mer telomerase reverse transcriptase (TERT) peptide, and human TERT, the rate-limiting subunit of the telomerase complex, is an attractive target for cancer vaccination." (PMID 27655706, 2016). "Re-activation of TERT is observed in multiple cancers, indicating that TERT is likely driving increased telomerase activity for these malignant cells." (PMID 27825130, 2016). "A typical example is the Myc/Max/Mad network proteins, the master regulator of the TERT transcription widely dysregulated in human cancer." (PMID 27438857, 2016). "In this study we extend our previous observations, which suggest a clinical role for the methylation signature of the TERT promoter in cancer." (PMID 27437772, 2016). "Another study in 234 cancer patients with 28 different types of cancer showed the patients’ serum TERT mRNA levels correlated with the clinical parameters of metastasis and recurrence (P < 0.001)." (PMID 27240403, 2016). "For the 6 independent susceptibility loci that have been identified in the TERT-CLPTM1L gene region, the same alleles are associated with an increased risk for some cancers but decreased risk of others." (PMID 27579533, 2016). "TERT promoter methylation status has unveiled a complex methylation pattern with some studies reporting hypomethylation in the CpG island in the TERT promoter region while others have described increased DNA methylation in TERT-expressing cancer cells." (PMID 27501725, 2016). "NTR produced by TERT/TERC active cancer cells then converts the pro-drug CB1954 into active cytotoxic 2- and 4-hydroxylamino derivatives that form DNA crosslinks via an N-acetoxy intermediate." (PMID 27240403, 2016). "GV1001 is a telomerase-based cancer vaccine made of a 16-mer TERT peptide, an attractive target for cancer vaccination and the main purpose of this study was to explore the effect of GV1001 when it was combined with gemcitabine in the treatment of PDAC." (PMID 27655706, 2016). "Telomerase activation is observed in the majority of human cancers, and TERT, which is normally suppressed, is frequently over-expressed in cancer cells." (PMID 26870890, 2016). "In many cancers, up-regulating TERT mRNA expression and down-regulating tumor suppressor genes such as Rb and p16 can achieve immortality." (PMID 27242892, 2016).